RNF133 (ring finger protein 133)
Description:
Has E3 ubiquitin-protein ligase activity (By similarity). Plays a role in male fecundity through the interaction with the E2 ubituitin-protein ligase UBE2J1.
Tractability: Antibody: UniProt predicts a signal peptide or a membrane-spanning region. PROTAC: UniProt records ubiquitination sites on it.
Gene: Protein-coding gene on chromosome 7 (122,697,735 to 122,699,117, reverse strand). Ensembl gene ENSG00000188050.
Subcellular location: Endoplasmic reticulum membrane
Gene Ontology:
Molecular function: ubiquitin protein ligase activity
Biological process: ubiquitin-dependent protein catabolic process; protein autoubiquitination; protein ubiquitination
Cellular component: endoplasmic reticulum membrane; endoplasmic reticulum; Golgi apparatus; late endosome
Genetic constraint (gnomAD): Loss-of-function variants: 0 observed, 0.55 expected, observed/expected ratio (o/e) 0, 90% interval 0 to 1.83. That is too few expected variants to judge how well the gene tolerates losing a copy. Missense variants: 469 observed, 474.69 expected, observed/expected ratio (o/e) 0.99, 90% interval 0.92 to 1.07. Synonymous variants: 153 observed, 160.09 expected, observed/expected ratio (o/e) 0.96, 90% interval 0.84 to 1.09.
Homologues: Orthologues: mouse Rnf133 (74% identical), rat Rnf133 (73% identical), guinea pig RNF133 (62% identical). Paralogues in human: RNF128 (48% identical), RNF148 (45% identical), RNF150 (30% identical), RNF149 (29% identical), RNF130 (27% identical), RNF13 (20% identical), RNF167 (20% identical), ZNRF4 (16% identical), RNF215 (14% identical).
Diseases named in the same sentence as RNF133 in open-access papers:
RNF133 is named in the same sentence as 4 diseases in open-access papers, as found by Europe PMC text mining. Sharing a sentence is not in itself a finding about the gene and the disease. The quoted sentences say what the papers report.
Infertility (2 papers, 2022 to 2025). "Nevertheless, as RNF133 deficiency only leads to subfertility while UBE2J1 deficiency leads to total infertility, additional factors may play a role in this process." (PMID 40412517, 2025).
Parkinson disease (1 paper, 2024). A progressive degenerative disorder of the central nervous system characterized by loss of dopamine producing neurons in the substantia nigra and the presence of Lewy bodies in the substantia nigra and locus coeruleus. "Sporadic missense variants in RNF133 (MIM# 620556) have been reported in patients with DD and ASD, while missense variants in ZNF746 (MIM# 613914) are reported in patients with Parkinson’s disease, and DD." (PMID 39519104, 2024).
RNF133 also shares sentences with these, for which no sentence is quoted: autism (1 paper); colorectal cancer (1).